TGFB3 (transforming growth factor beta 3)
Description:
Transforming growth factor beta-3 proprotein: Precursor of the Latency-associated peptide (LAP) and Transforming growth factor beta-3 (TGF-beta-3) chains, which constitute the regulatory and active subunit of TGF-beta-3, respectively. [Latency-associated peptide]: Required to maintain the Transforming growth factor beta-3 (TGF-beta-3) chain in a latent state during storage in extracellular matrix (By similarity). Associates non-covalently with TGF-beta-3 and regulates its activation via interaction with 'milieu molecules', such as LTBP1 and LRRC32/GARP, that control activation of TGF-beta-3 (By similarity). Interaction with integrins results in distortion of the Latency-associated peptide chain and subsequent release of the active TGF-beta-3 (By similarity). Transforming growth factor beta-3: Multifunctional protein that regulates embryogenesis and cell differentiation and is required in various processes such as secondary palate development (By similarity). Activation into mature form follows different steps: following cleavage of the proprotein in the Golgi apparatus, Latency-associated peptide (LAP) and Transforming growth factor beta-3 (TGF-beta-3) chains remain non-covalently linked rendering TGF-beta-3 inactive during storage in extracellular matrix (By similarity). At the same time, LAP chain interacts with 'milieu molecules', such as LTBP1 and LRRC32/GARP that control activation of TGF-beta-3 and maintain it in a latent state during storage in extracellular milieus (By similarity). TGF-beta-3 is released from LAP by integrins: integrin-binding results in distortion of the LAP chain and subsequent release of the active TGF-beta-3 (By similarity). Once activated following release of LAP, TGF-beta-3 acts by binding to TGF-beta receptors (TGFBR1 and TGFBR2), which transduce signal (By similarity).
Synonyms: ARVD; ARVD1; LDS5; RNHF; TGF-beta3
Tractability: Antibody: a drug acting on it is in phase 2 or 3 trials; its Gene Ontology location is reachable by antibodies, with high confidence; UniProt places it where antibodies can reach, with medium confidence; UniProt predicts a signal peptide or a membrane-spanning region. PROTAC: ubiquitination databases record sites on it. Other modalities: an approved drug acts on it.
Target class: Secreted protein
Gene: Protein-coding gene on chromosome 14 (75,958,097 to 75,983,026, reverse strand). Ensembl gene ENSG00000119699.
Subcellular location: Secreted, extracellular space, extracellular matrix (Latency-associated peptide); Secreted (Transforming growth factor beta-3)
Subcellular location (Human Protein Atlas): Vesicles; Basal body; Centriolar satellite; Nucleoplasm; Predicted to be secreted
Pathways (Reactome):
Extracellular matrix organization: ECM proteoglycans; Molecules associated with elastic fibres
Hemostasis: Platelet degranulation
Signal Transduction: TGF-beta receptor signaling activates SMADs
Gene Ontology:
Molecular function: identical protein binding; protein binding; transforming growth factor beta binding; type I transforming growth factor beta receptor binding; type II transforming growth factor beta receptor binding; type III transforming growth factor beta receptor binding; cytokine activity; growth factor activity; transforming growth factor beta receptor binding
Biological process: cell-cell junction organization; detection of hypoxia; face morphogenesis; negative regulation of cell population proliferation; negative regulation of macrophage cytokine production; negative regulation of vascular associated smooth muscle cell proliferation; positive regulation of cell population proliferation; positive regulation of collagen biosynthetic process; positive regulation of DNA-templated transcription; positive regulation of epithelial to mesenchymal transition; positive regulation of protein secretion; positive regulation of stress fiber assembly; positive regulation of tight junction disassembly; response to hypoxia; response to progesterone; salivary gland morphogenesis; transforming growth factor beta receptor signaling pathway; heart development; in utero embryonic development; lung alveolus development; mammary gland development; negative regulation of neuron apoptotic process; odontogenesis; positive regulation of apoptotic process; positive regulation of filopodium assembly; and 11 more
Cellular component: extracellular matrix; extracellular region; plasma membrane; platelet alpha granule lumen; transforming growth factor beta complex
Genetic constraint (gnomAD): Loss-of-function variants: 5 observed, 42.2 expected, observed/expected ratio (o/e) 0.12, 90% interval 0.061 to 0.25. The upper end of that interval is the gene's LOEUF score, 0.25, which puts it in group 1 of 6, group 1 being the genes least tolerant of losing a copy. Missense variants: 373 observed, 558.39 expected, observed/expected ratio (o/e) 0.67, 90% interval 0.61 to 0.73. Synonymous variants: 184 observed, 218.77 expected, observed/expected ratio (o/e) 0.84, 90% interval 0.75 to 0.95.
Gene-disease validity (ClinGen):
ClinGen rates the evidence that TGFB3 causes each of these diseases.
arrhythmogenic right ventricular cardiomyopathy (autosomal dominant): Limited.
familial thoracic aortic aneurysm and aortic dissection (autosomal dominant): Limited. A rare genetic vascular disease characterized by the familial occurrence of thoracic aortic aneurysm, dissection or dilatation affecting one or more aortic segments (aortic root, ascending aorta, arch or descending aorta) in the absence of any other associated disease.
Homologues: Orthologues: chimpanzee TGFB3 (100% identical), macaque TGFB3 (99% identical), guinea pig TGFB3 (99% identical), dog TGFB3 (98% identical), rabbit TGFB3 (98% identical), rat Tgfb3 (98% identical), mouse Tgfb3 (98% identical), pig TGFB3 (91% identical), zebrafish tgfb3 (73% identical), tropical clawed frog tgfb1 (43% identical). Paralogues in human: TGFB2 (55% identical), TGFB1 (44% identical), MSTN (25% identical), BMP7 (24% identical), GDF11 (24% identical), BMP6 (23% identical), BMP4 (23% identical), BMP5 (23% identical), BMP8A (22% identical), BMP8B (22% identical), BMP2 (21% identical), BMP10 (21% identical), and 19 more.
Diseases named in the same sentence as TGFB3 in open-access papers:
TGFB3 is named in the same sentence as 265 diseases in open-access papers, as found by Europe PMC text mining. Sharing a sentence is not in itself a finding about the gene and the disease. The quoted sentences say what the papers report.
breast carcinoma (35 papers, 2003 to 2025). "AVID200 is a selective trap of TGFβ1 and TGFβ3 that has shown antitumor efficacy in breast cancer models in mice (4T1 cells)." (PMID 38256140, 2024). "In the present study, high TGFB3 expression was identified as a favorable prognostic indicator which contrasts with its reported adverse prognostic role in breast cancer." (PMID 36980562, 2023). "In conclusion, we propose that invasive breast cancer cells interfere with the adipogenic differentiation potential of bmMSCs via the induction of HA in bmMSC mediated in part by TGFβ3." (PMID 34707175, 2021). "As a positive control to validate the antibody, we ran protein extracts from MCF7 cells, a hormone-responsive breast cancer cell line known to express TGFβ3, alongside protein extracts from human cumulus cells." (PMID 34063149, 2021). "Factor 12 also predicts insensitivity to TOP1-poisons and includes the canonical oncogenes such as ERBB2, TGFB3, ESR1 (AR), and FGFR4 that are strongly associated with breast cancer." (PMID 31695042, 2019). "Other differentially expressed genes associated with more aggressive breast cancer including ERBB4 and TGFB3 are up-regulated in poor responders in these data." (PMID 27090210, 2016). "The association of TGFB3 mRNA expression with breast cancer prognosis and PABC remains somewhat elusive, especially since TGFB3 is highly regulated at the post-translational level." (PMID 26618099, 2015). "Having thus far only evaluated TGFβ3’s contribution to tumor suppression, we wanted to address the other, pro-metastatic arm of the TGFβ family’s dual role in cancer – a concern due to frequent extrapolation of data relating to TGFβ1’s role in promoting breast cancer to TGFβ3." (PMID 38831405, 2024). "In fact, in general breast cancer datasets, TGFβ3 seems to be protective against breast cancer." (PMID 38831405, 2024). "Additionally, high TGFB3 expression has been reported to have a favorable prognostic effect in breast cancer, ovarian cancer, and colon cancer." (PMID 36980562, 2023). "Similarly, we chose RHOA, MKI67, CITED2, ACTA2, FN1 and TGFB3, as all have been implicated in EMT and highly metastatic breast cancer." (PMID 23441166, 2013). "In addition, our study highlights TGFβ3 as a predictive marker to inform patient stratification for palbociclib treatment in breast cancer, underscoring the robustness of in vivo genome-wide CRISPR screening approaches to identify actionable biomarkers of drug response." (PMID 38831405, 2024). "At least four well-known breast cancer genes including SMAD2, SMAD4, TGFB3 and TGFBR3 are involved in palate development." (PMID 23281707, 2012). "Notably, the transcripts of PEAK1-suppressed MSC factors (i.e., TGFB3, VEGFA and CSF1) were significantly lower within breast cancer stroma (left three graphs)." (PMID 34239043, 2021). "The TGF– β family is involved in most of the considered diseases, e.g., TGFB1 in Osteoporosis, TGFB3 in Rheumatoid arthritis, Osteoarthritis and Multiple myeloma, TGFBR2 in HIV, Osteomyelitis and Measles, BMP in Breast cancer and Osteosarcoma, and BMP3 in Periodontitis." (PMID 30497370, 2018).
cleft palate (22 papers, 2009 to 2025). Cleft palate is a fissure type embryopathy that affects the soft and hard palate to varying degrees. "For instance, pathogenic variants in the TGFB1 and TGFB3 genes are linked to the development of cleft lip and cleft palate, conditions that are frequently observed in individuals with LDS." (PMID 40282317, 2025). "Transforming growth factor-beta 3 (Tgfb3) has been established as a critical gene for causing cleft palate through regulating epithelial fusion in mice and humans." (PMID 34897389, 2022). "For example transient transduction of the periderm via intra-amniotic delivery of adenoviral vector encoding transforming growth factor β3 (TGFβ3) prevents cleft palate in a mouse model of disease." (PMID 31406195, 2019). "Mutations in the human TGFB3 have been linked to cleft palate, and a recent report described a disease-causing mutation in the coding region of TGFB3 in patients showing abnormalities in palate and muscle development." (PMID 25071603, 2014). "We identified potential causative CP genes in a TGFβ3 knockout model, which may lead to a better understanding of the genetic mechanisms of palatogenesis and provide novel potential targets for gene therapy approaches to treat cleft palate." (PMID 23421592, 2013). "This has been shown by deletions of TGFβ2, TGFβ3 and Inhibin βA, which all result in cleft palate defects in the respective mouse model." (PMID 26447543, 2015). "TGFβ3 has been found to have a vital role in palatogenesis as TGFβ3 homozygous null mice develop a cleft palate due to a failure in the fusion process, while the exogenous addition of TGFβ3 can reverse cleft palate development in mice." (PMID 23382716, 2013). "Another study suggested that the canonical Wnt signaling via ß-Catenin is responsible for the MEE-specific Tgfb3 gene expression, since deletion of the Ctnnb1 gene by a commonly used Keratin 14-Cre (K14Cre) mouse line almost completely abolished Tgfb3 expression in the MEE resulting in cleft palate." (PMID 37250135, 2023). "Our combined results provide an initial understanding of the complex genetic mechanism of TGFβ3-mediated palatogenesis, and may lead to the identification of genes for the targeted prenatal treatment of cleft palate." (PMID 23421592, 2013). "Many studies have focused on a number of human populations to establish whether the role of TGFβ3 in cleft palate development can be applicable to humans." (PMID 23382716, 2013). "Unlike the previous case, the newborn presented a cleft palate and minor dysmorphisms but no alteration on the echocardiographic examination, although the genetic test confirmed the presence of a pathogenetic variant of TGFB3." (PMID 36138598, 2022). "However, it is highly plausible that there are complex interactions between many growth factors, which may explain why different strains of TGFβ3 homozygous null mice develop different phenotypes of cleft palate." (PMID 23382716, 2013). "Furthermore, we identified 8 key genes which may play fundamental roles in the development of cleft palate in TGFβ3−/− mice." (PMID 23421592, 2013). "Thus, it could be that TGFβ3 is of importance in cleft palate development but only in certain populations." (PMID 23382716, 2013). "This will establish whether there is a difference in Has expression in different phenotypes of cleft palate, which have developed due to absence of TGFβ3." (PMID 23382716, 2013). "Finally, Guo and collaborators investigated the interplay between two genetic variations (i.e., C641A and G15572) within transforming growth factor beta 3 (TGFb3) and maternal exposures during pregnancy in relation to the occurrence of cleft lip with/without cleft palate (CL/P)." (PMID 38613027, 2024).
leiomyoma (22 papers, 2008 to 2026). A well-circumscribed benign smooth muscle neoplasm characterized by the presence of spindle cells with cigar-shaped nuclei, interlacing fascicles, and a whorled pattern. "Fibroids can also lead to subfertility by causing an increase in endometrial pan-leukocyte density, a decrease in natural killer cell density, involuntary contraction in myocytes, and the release of transforming-growth-factor-beta 3 (TGF-β3)." (PMID 36430682, 2022). "For example, by producing excessive amount of TGFB3, leiomyoma antagonizes decidualization mediated by BMP2." (PMID 25478164, 2014). "Among all the three TGFβ isoforms, TGFB3 seems to play a major role in leiomyoma development by promoting cell growth and fibrogenic process." (PMID 25478164, 2014). "Tgfb3 transcript and protein levels are elevated in human leiomyoma cells, compared with myometrial cells in two-dimensional (2D) and 3D cultures." (PMID 25478164, 2014). "In a 3D culture system, a higher level of TGFB3 and SMAD2/3 activation is present in the leiomyoma cells versus myometrial cells." (PMID 25478164, 2014). "In UPA-treated myomas, in comparison with the untreated ones, a significantly lower TGFβ3 concentration was shown by other studies, pointing towards the fact that this could be a possible inhibitory mechanism of UPA action in fibroids." (PMID 34442017, 2021). "In this vein, asoprisnil, a steroidal 11β-benzaldoxime-substituted selective progesterone receptor modulator (SPRM), targets TGFB3 and TGFBR2 in leiomyoma cells but not normal myometrial cells, providing a potentially effective treatment option for leiomyoma." (PMID 25478164, 2014).
liver fibrosis (17 papers, 2013 to 2025). "Of note, we found that at MH stage, loss of FOXA2 led to a significant increase in the expression of mRNA levels of genes associated with hepatic fibrosis and HSC activation, such as PDGF, MMP2, TGFβ2, TGFβ3, TGFβR2, and DLK1 among others." (PMID 35973994, 2022). "For example, overexpression of TGFβ3 was reported to reduce the histopathological damage observed in liver fibrosis." (PMID 36425072, 2022). "Although we have identified the tipping point as well as a potentially important function of Tgfb3 in TAA‐induced mice model of liver fibrosis, the results warrant further validation in other animal models or in patients with chronic liver diseases." (PMID 33269546, 2021). "In Con A‐induced autoimmune liver‐damaged mice, abnormal HSC activation was accompanied by imbalance of Tgfb1 and Tgfb3 expressions in the early stage, which can line immune and hepatic fibrosis processes, leading to further switching and progressing of liver fibrosis." (PMID 33269546, 2021). "The expression of Tgfb3 increased earlier than Tgfb1 in vivo in the liver of mice with TAA‐induced experimental liver fibrosis, suggesting that Tgfb3 may be more important than Tgfb1 in initiating fibrogenesis." (PMID 33269546, 2021). "Many of these genes, including COL1A1, LOX, MMP14, TGFB3, TIMP1 and VCAN, are known markers for liver fibrosis." (PMID 34588551, 2021). "The canonical pathway Hepatic Fibrosis/Activation of Hepatic Stellate Cells was the pathway most significantly represented in all three groups (CD24 Up, CD24 Down, and TGFβ3)." (PMID 26788063, 2016).
pulmonary fibrosis (13 papers, 2017 to 2026). Chronic progressive interstitial lung disorder characterized by the replacement of the lung tissue by connective tissue, leading to progressive dyspnea, respiratory failure, or right heart failure. "Further, inhibiting both TGFβ2 and TGFβ3 while sparing TGFβ1 could alleviate lung fibrosis while avoiding toxicity concerns associated with pan-TGFβ blockade." (PMID 34785671, 2021). "Steroids may attenuate pulmonary fibrosis through the modulation of transforming growth factor beta-3 in patients with ILD-PF and infection, thereby reducing hypoxemia." (PMID 34705851, 2021).